PIBF1 (progesterone immunomodulatory binding factor 1)
Description:
Plays a role in ciliogenesis. [Isoform 1]: Pericentriolar protein required to maintain mitotic spindle pole integrity. Required for the centrosomal accumulation of PCM1 and the recruitment of centriolar satellite proteins such as BBS4. Via association with PCM1 may be involved in primary cilia formation. Required for CEP63 centrosomal localization and its interaction with WDR62. Together with CEP63 promotes centriole duplication. Promotes the centrosomal localization of CDK2. [Isoform 4]: The secreted form is a mediator of progesterone that by acting on the phospholipase A2 enzyme interferes with arachidonic acid metabolism, induces a Th2 biased immune response, and by controlling decidual natural killer cells (NK) activity exerts an anti-abortive effect. Increases the production of Th2-type cytokines by signaling via the JAK/STAT pathway. Activates STAT6 and inhibits STAT4 phosphorylation. Signaling via a not identified receptor seems to implicate IL4R and a GPI-anchored protein.
Synonyms: PIBF; CEP90; C13orf24; JBTS33
Tractability: Antibody: UniProt places it where antibodies can reach, with high confidence; its Gene Ontology location is reachable by antibodies, with medium confidence. PROTAC: ubiquitination databases record sites on it; its protein half-life has been measured.
Gene: Protein-coding gene on chromosome 13 (72,781,641 to 73,017,823, forward strand). Ensembl gene ENSG00000083535.
Subcellular location: Cytoplasm, cytoskeleton, microtubule organizing center, centrosome; Cytoplasm; Secreted; Nucleus (Isoform 1); Cytoplasm, cytoskeleton, microtubule organizing center, centrosome, centriolar satellite; Secreted (Isoform 4)
Subcellular location (Human Protein Atlas): Centriolar satellite; Centrosome; Basal body; Predicted to be secreted
Gene Ontology:
Molecular function: interleukin-4 receptor binding; protein binding
Biological process: activation of Janus kinase activity; cilium assembly; mitotic metaphase chromosome alignment; mitotic spindle assembly; negative regulation of interleukin-12 production; negative regulation of natural killer cell activation; negative regulation of prostaglandin biosynthetic process; negative regulation of tyrosine phosphorylation of STAT protein; non-motile cilium assembly; positive regulation of interleukin-10 production; positive regulation of tyrosine phosphorylation of STAT protein; protein localization to centrosome
Cellular component: centriolar satellite; centrosome; cytoplasm; extracellular region; nucleus; microtubule organizing center
Genetic constraint (gnomAD): Loss-of-function variants: 23 observed, 26.39 expected, observed/expected ratio (o/e) 0.87, 90% interval 0.63 to 1.24. The upper end of that interval is the gene's LOEUF score, 1.24, which puts it in group 5 of 6, group 1 being the genes least tolerant of losing a copy. Missense variants: 286 observed, 259.83 expected, observed/expected ratio (o/e) 1.1, 90% interval 1 to 1.21. Synonymous variants: 93 observed, 89.93 expected, observed/expected ratio (o/e) 1.03, 90% interval 0.87 to 1.23.
Homologues: Orthologues: chimpanzee PIBF1 (99% identical), macaque PIBF1 (97% identical), rabbit PIBF1 (92% identical), dog PIBF1 (91% identical), guinea pig PIBF1 (90% identical), pig PIBF1 (89% identical), mouse Pibf1 (89% identical), rat Pibf1 (89% identical), tropical clawed frog pibf1 (70% identical), zebrafish pibf1 (65% identical).
Diseases named in the same sentence as PIBF1 in open-access papers:
PIBF1 is named in the same sentence as 36 diseases in open-access papers, as found by Europe PMC text mining. Sharing a sentence is not in itself a finding about the gene and the disease. The quoted sentences say what the papers report.
Joubert syndrome (7 papers, 2019 to 2023). Joubert syndrome (JS) is characterized by congenital malformation of the brainstem and agenesis or hypoplasia of the cerebellar vermis leading to an abnormal respiratory pattern, nystagmus, hypotonia, ataxia, and delay in achieving motor milestones. "Although this variant is likely-pathogenic and associated with Joubert syndrome in ClinVar, it has been reported in a heterozygous compound context with a genomic deletion encompassing PIBF1 coding regions." (PMID 36140829, 2022). "We identified two pathogenic variants (NM_006346.2: c.1147delC and c.1054A > G) of PIBF1 in this Joubert syndrome individual, which is consistent with the mode of autosomal recessive inheritance." (PMID 33004012, 2020). "In this study, we identified two novel pathogenic variants in PIBF1 in a Joubert syndrome individual using whole exome sequencing, thereby expanding the PIBF1 pathogenic variant spectrum of Joubert syndrome." (PMID 33004012, 2020). "In this study, we identified two novel pathogenic variants on PIBF1 in a Joubert syndrome individual using whole exome sequencing." (PMID 33004012, 2020). "Interestingly, five of the potential interactors (PIBF1, CSPP1, OFD1, C2CD3, and KIF7) have been linked to a single ciliopathy, the Joubert syndrome, reinforcing the role of CCP6 activity in cilia regulation." (PMID 36674791, 2023). "Intriguingly, five of the candidate interactors found in our BioID-based interactomic study (i.e., C2CD3, PIBF1, CSPP1, OFD1, and KIF7) are related to a single rare pathology, the Joubert syndrome." (PMID 36674791, 2023). "In contrast, the Joubert syndrome cluster contained five hits found under starved conditions, CPLANE1, UNC119, PIBF1, and CEP164." (PMID 34685691, 2021).
ciliopathy (4 papers, 2021 to 2024). A genetic disorder of the cellular cilia or the cilia anchoring structures, the basal bodies, or of ciliary function. "We focused further our functional analysis on the candidate centriolar protein CEP90/PIBF1 as (i) CEP90 gene was found mutated in some ciliopathies; and (ii) CEP90 is well conserved from protists to mammals, despite being absent in some phyla." (PMID 36070319, 2022). "Among its potential interactants, we focused our study on CEP90/PIBF1, since its encoding gene was found mutated in some ciliopathies." (PMID 36070319, 2022).
microcephaly (2 papers, 2015 to 2019). A congenital or acquired developmental disorder in which the circumference of the head is smaller than normal for the person's age and sex. "The microcephaly of the patient is not part of the classical JS spectrum, but has been reported in a patient with a PIBF1 missense mutation." (PMID 30858804, 2019).
breast tumours (1 paper, 2016). "In the 13q22.1 locus, the strongest eQTLs in the 735 TCGA breast tumours (BC765) involved PIBF1." (PMID 27117709, 2016).
Cerebellar hypoplasia (1 paper, 2022). Cerebellar hypoplasia is a descriptive term implying a cerebellum with a reduced volume, but a normal shape and is stable over time. "Recently, a large exome sequencing study of children and adults with DWM and cerebellar hypoplasia expanded the list of genes associated with DWM to include TUBA1A, BRAF, SETD2, FOXP1, PUS3, ARMC9, and PIBF1." (PMID 35202430, 2022).
emphysema (1 paper, 2021). "In this study, we identified one genome-wide significant SNP in a novel candidate gene (PIBF1) and candidate SNPs (P < 5.0 × 10–6) for quantitative emphysema on CT in all subjects and COPD patients in Korean cohorts." (PMID 34404834, 2021).
gout (1 paper, 2020). A condition characterized by painful swelling of the joints, which is caused by deposition of urate crystals. "Of these, two loci from all gout types, rs76499759 of PIBF1 and rs9926388 of ACSM2B, and another two intergenic loci from normal type gout, rs146978188 of CD2-PTGFRN and rs548944057 of SLC28A3-NTRK2, were detected as novel loci." (PMID 32238385, 2020).
infertile (1 paper, 2022). "Elaborating on that, data provided from a recently published study indicate a reduction in the expression levels of progesterone-induced blocking factor 1 (PIBF1) in the mid-secretory endometrium in RIF patients compared to a non-RIF infertile group." (PMID 35216313, 2022).
lung adenocarcinoma (1 paper, 2023). A carcinoma that arises from the lung and is characterized by the presence of malignant glandular epithelial cells. "In conclusion, we provide clinical evidence of a novel PIBF1-RET oncogenic fusion in early-stage lung adenocarcinoma." (PMID 37478265, 2023). "Herein, we report a novel progesterone immunomodulatory binding factor 1 (PIBF1)-RET gene fusion identified from a stage IA lung adenocarcinoma and was further validated by RNA sequencing analysis." (PMID 37478265, 2023). "We report a novel PIBF1-RET fusion in early-stage lung adenocarcinoma." (PMID 37478265, 2023).
lung carcinoma (1 paper, 2023). "Molecular testing with a targeted panel of 8 lung cancer-associated driver genes detected a novel PIBF1-RET (P16:R12) fusion, which putatively encodes a gene in which the first 16 exons of PIBF1 was concatenated to RET exon 13 and its downstream sequence, retaining the RET kinase domain." (PMID 37478265, 2023).
schizophrenia (1 paper, 2012). A major psychotic disorder characterized by abnormalities in the perception or expression of reality. "Five were not located in any gene, and four were located in genes (ATP8A2, LHFP, PHF11, RCBTB1, and PIBF1 (C13orf24)) not yet shown to be associated with schizophrenia." (PMID 22214315, 2012).
tumor (6 papers, 2015 to 2025). "Considering that PIBF1 breakpoints were predominantly observed in the distal part of the gene it is tempting to speculate that PIBF1 gene breakpoints disrupt its nuclear localization signal upon which it becomes a secreted protein with anti-tumor immune-suppressing capabilities." (PMID 26375816, 2015).
PIBF1 also shares sentences with these, for which no sentence is quoted: cancer (3 papers); glioblastoma (3); leukemia (3); astrocytomas (2); infection (2); Miscarriage (2); brain tumors (1); breast carcinoma (1); cervical cancer (1); cervical intraepithelial neoplasia (1); cervicitis (1); endometrial cancer (1); endometriosis (1); fibrosarcoma (1); gastric cancer (1); Intellectual disability (1); Jeune syndrome (1); Joubert syndrome 33 (1); osteosarcoma (1); ovarian carcinoma (1); pericardial effusion (1); retinal diseases (1); thyroid autoimmunity (1); thyroid cancer (1).